GGA1 (golgi associated, gamma adaptin ear containing, ARF binding protein 1)
Description:
Plays a role in protein sorting and trafficking between the trans-Golgi network (TGN) and endosomes. Mediates the ARF-dependent recruitment of clathrin to the TGN and binds ubiquitinated proteins and membrane cargo molecules with a cytosolic acidic cluster-dileucine (DXXLL) motif. Mediates export of the GPCR receptor ADRA2B to the cell surface. Required for targeting PKD1:PKD2 complex from the trans-Golgi network to the cilium membrane (By similarity). Regulates retrograde transport of proteins such as phosphorylated form of BACE1 from endosomes to the trans-Golgi network.
Tractability: Small molecule: a structure with a bound ligand is known. Antibody: UniProt places it where antibodies can reach, with high confidence. PROTAC: UniProt records ubiquitination sites on it; ubiquitination databases record sites on it; its protein half-life has been measured.
Gene: Protein-coding gene on chromosome 22 (37,608,474 to 37,633,564, forward strand). Ensembl gene ENSG00000100083.
Subcellular location: Golgi apparatus, trans-Golgi network membrane; Endosome membrane; Early endosome membrane
Subcellular location (Human Protein Atlas): Golgi apparatus; Vesicles; Nucleoplasm
Pathways (Reactome):
Metabolism of proteins: Amyloid fiber formation
Vesicle-mediated transport: TBC/RABGAPs
Gene Ontology:
Molecular function: protein binding; small GTPase binding; phosphatidylinositol binding; ubiquitin binding
Biological process: Golgi to plasma membrane protein transport; intracellular protein localization; intracellular protein transport; protein localization to cell surface; retrograde transport, endosome to Golgi; Golgi to plasma membrane transport; protein localization to ciliary membrane; vesicle-mediated transport
Cellular component: early endosome; early endosome membrane; endosome membrane; Golgi apparatus; membrane; protein-containing complex; trans-Golgi network; cytosol
Genetic constraint (gnomAD): Loss-of-function variants: 14 observed, 46.75 expected, observed/expected ratio (o/e) 0.3, 90% interval 0.2 to 0.47. The upper end of that interval is the gene's LOEUF score, 0.47, which puts it in group 2 of 6, group 1 being the genes least tolerant of losing a copy. Missense variants: 582 observed, 660.49 expected, observed/expected ratio (o/e) 0.88, 90% interval 0.82 to 0.94. Synonymous variants: 281 observed, 281.87 expected, observed/expected ratio (o/e) 1, 90% interval 0.9 to 1.1.
Homologues: Orthologues: chimpanzee GGA1 (99% identical), macaque GGA1 (98% identical), dog GGA1 (93% identical), guinea pig GGA1 (93% identical), pig GGA1 (93% identical), rat Gga1 (92% identical), mouse Gga1 (91% identical), tropical clawed frog gga1 (68% identical), zebrafish gga1 (64% identical), Drosophila melanogaster Gga (29% identical), Drosophila melanogaster Stam (11% identical), Caenorhabditis elegans stam-1 (9% identical), and 2 more. Paralogues in human: GGA3 (55% identical), GGA2 (46% identical), TOM1L2 (21% identical), TOM1 (19% identical), HGS (15% identical), TOM1L1 (15% identical), STAM (14% identical), STAM2 (13% identical), WDFY2 (10% identical), WDFY1 (10% identical).
Diseases named in the same sentence as GGA1 in open-access papers:
GGA1 is named in the same sentence as 12 diseases in open-access papers, as found by Europe PMC text mining. Sharing a sentence is not in itself a finding about the gene and the disease. The quoted sentences say what the papers report.
Alzheimer disease (5 papers, 2011 to 2024). A progressive, neurodegenerative disease characterized by loss of function and death of nerve cells in several areas of the brain leading to loss of cognitive function such as memory and language. "The dysregulation of GGA1-mediated sorting processes could contribute to the accumulation of amyloid-beta plaques, a hallmark of Alzheimer’s disease." (PMID 38255751, 2024). "GGA1 has been associated with neurodegenerative disorders, particularly Alzheimer’s disease." (PMID 38255751, 2024). "Decreased levels of GGA1 and GGA3 have been described for Alzheimer's disease." (PMID 28722658, 2017). "In addition, the GAT domains of human GGA1 and GGA3, but not GGA2, bind ubiquitin and ubiquitinated proteins, and GGA1 and GGA3, but not GGA2, are depleted in the brains of patients with Alzheimer disease." (PMID 24637350, 2014).
Hypoglycemia (2 papers, 2012). A decreased concentration of glucose in the blood. "Furthermore, other than small size and perinatal hypoglycemia, the phenotypes were uninformative as to the basis for lethality of GGA2 mutant mice or GGA1/GGA3 double mutant mice." (PMID 23028818, 2012).
Infertility (1 paper, 2023). "Gga1 ablation led to infertility in male mice exposed to BPA, along with a significant reduction in sperm count, sperm motility and the percentage of normal sperm." (PMID 37551344, 2023). "To explore the reason of the infertility of BPA-treated Gga1−/− male mice, we performed a histological analysis of the caudal epididymis by H&E staining and found fewer spermatozoa in the epididymal lumen of BPA-treated Gga1−/− mice than that of BPA-treated Gga1+/+ mice." (PMID 37551344, 2023).
male infertility (1 paper, 2023). The inability of the male to effect fertilization of an ovum after a specified period of unprotected intercourse. "To discover the cause of male infertility and reduced testis size, furtherly, we examined the testes of Gga1+/+ and Gga1−/− mice by H&E staining." (PMID 37551344, 2023). "Gga1 may be a potential target for therapy of male infertility caused by environmental pollutants." (PMID 37551344, 2023).
neuroblastoma (1 paper, 2024). Neuroblastoma (NB) is the most common solid, extracranial childhood tumor. "We corroborated the NHE6-GGA1 interaction using: coimmunoprecipitation; overexpressed constructs in mammalian cells; and coimmunoprecipitation of endogenously expressed GGA1 and NHE6 from neuroblastoma cells, as well as from the mouse brain." (PMID 39002678, 2024).
tumor (4 papers, 2018 to 2024). "Altered expression levels of GGA1 have been observed in various cancer types, and it appears to be involved in the trafficking of proteins associated with tumour growth and metastasis." (PMID 38255751, 2024). "The risk score of each patient was calculated using the following formula based on their regression coefficient of the expression levels of these 3 markers: risk score = 0.003 × Hscore of FHL3 in tumor -0.006× Hscore of GGA1 in tumor +0.004× Hscore of TGFBI in stromal." (PMID 37258779, 2023). "Similarly, expressions of both GGA1 and GGA3 were higher in some tumor regions than in non-tumor regions, but the increases were not statistically significant." (PMID 29358589, 2018).
cancer (3 papers, 2018 to 2024). A tumor composed of atypical neoplastic, often pleomorphic cells that invade other tissues. "However, because the present data also indicated that the protein expressions of GGA1 and/or GGA3 were also increased in some cancer tissues, relative amounts of GGA1, 2, and 3 could determine the EGFR stability." (PMID 29358589, 2018).
infection (1 paper, 2012). The state of being infected such as from the introduction of a foreign agent such as serum, vaccine, antigenic substance or organism. "S. nodorum gna1, gba1 and gga1 were all unable to sporulate during infection of the wheat leaf, however although this defect may slow disease amplification, sporulation is clearly not a prerequisite for leaf necrosis." (PMID 22759704, 2012).
neurodegenerative disease (1 paper, 2021). A disorder of the central nervous system characterized by gradual and progressive loss of neural tissue and neurologic function. "Here, we detected the altered level of GGA1, a Golgi protein that controls APP processing and Golgi alterations, suggesting that Aβ accumulation (a known hallmark in different neurodegenerative diseases) might be involved in cellular perturbations in DNAJC3mutcells." (PMID 34692675, 2021).
GGA1 also shares sentences with these, for which no sentence is quoted: autism (1 paper); pilocytic astrocytoma (1); schizophrenia (1).